STAT3 (signal transducer and activator of transcription 3)
Diseases named in the same sentence as STAT3 in open-access papers (continued):
Sharing a sentence is not in itself a finding about the gene and the disease.
tumor (continued). "In this study, we use in silico methods to analyze differential expression, prognostic value, genetic and epigenetic alterations, association with tumor-infiltrating immune cells, and cancer-associated fibroblast (CAF) infiltrations of STAT3/CDK2/4/6 in multiple cancer types." (PMID 33668805, 2021). "Epigenetic regulation of the JAK1/STAT3 pathway is common in many tumor cells." (PMID 34942997, 2021). "When CCA cells were exposed to IL-6, a key inflammatory factor in the CCA tumor microenvironment, the level of the m6A modification was significantly elevated, accompanied by higher expression levels of phosphorylated STAT3 in the CCA cells exposed to IL-6." (PMID 34347395, 2021). "MiR-519a functions as a tumour suppressor by directly targeting STAT3 in GBM." (PMID 34425834, 2021). "Therefore, HNF4α can alleviate or reverse tumor lesions by blocking the activation of the STAT3 signal transduction pathway and inhibiting the invasion and metastasis of cancer cells." (PMID 33462379, 2021). "The results show that overexpression of LTF may reduce the secretion of GM-CSF by tumor cells through JAK/STAT3 pathway to regulate the tumor immune microenvironment and inhibit tumor cell proliferation and migration." (PMID 34868909, 2021). "Moreover, protein levels of AGTR1, p-MEK, p-ERK1/2 and p-STAT3 in tumor tissues were significantly down-regulated in sh-LINC00852-1 group than sh-NC group." (PMID 34496800, 2021). "Furthermore, the CPT single treatment also significantly inhibited the activities of STAT3 and eIF4E signalling pathways in tumour tissues." (PMID 34214017, 2021). "Furthermore, Nanog and phosphorylated STAT3 in anticarin β-treated tumor tissues were decreased by immunofluorescent stain." (PMID 34408983, 2021). "They showed that high levels of the inflammatory cytokine Il-23 mediated paracrine effects on tumor-infiltrating MDSCs by activating downstream androgen receptor (AR) target genes through the signal transducer and activator of transcription 3 (STAT3)–RORγ signaling axis in tumor cells." (PMID 34502458, 2021). "IL10/STAT3 also promotes tumor proliferation and tumor metastasis via immunosuppression." (PMID 33500726, 2021). "Immunohistochemical detection of p-Stat3 was performed in nude mice in vivo model tumor tissue." (PMID 34736477, 2021). "Therefore, STAT3-related MDSCs generation is considered as a major obstacle to anti-tumor immunotherapy." (PMID 33957948, 2021). "Moreover, IL-6-induced tumor growth of HCC cells via STAT3 phosphorylation at tyrosine 705 in the presence of sorafenib is reversed with IL-6Rα depletion." (PMID 34948424, 2021). "Nuclear factor kappa beta and STAT3 hyperactivation in tumor cells and immune cells in the tumor microenvironment in turn promotes production of several pro-inflammatory cytokines including IL-1β, IL-6, and TNFα, which promote survival and proliferation of tumor cells." (PMID 35048057, 2021). "In addition to the factors (PD-1, indolamine 2, IDO, STAT3, FASL, TGF-B and IL-1), TME contain high amounts of tumor associated macrophages (TAMs); they are highly infiltrating and present in two different phenotypes, M1 and M2." (PMID 34948224, 2021). "The effect of napabucasin on tumor growth was associated with almost absent phosphorylation of STAT3 in the tumor cells despite normal STAT3 expression." (PMID 33530306, 2021). "miR-124 was observed to target STAT3 to repress tumor growth and metastasis in NPCs." (PMID 33917482, 2021). "Altogether, these results indicated that flubendazole was a potential antitumor agent that could significantly inhibit tumor development by suppressing the STAT3 signaling pathway as well as by stimulating autophagy." (PMID 34513827, 2021).
tumor (continued). "STAT3 activation in DCs significantly reduces tumor immune surveillance." (PMID 34976809, 2021). "We found that bufalin could inhibit the tube formation, adhesion and migration of HUVECs mediated by CAFs, TAMs and tumour cells by inhibiting the activation of HUVEC STAT3 and thereby decreasing the expression of VEGF, PDGFA, E-selectin, and P-selectin." (PMID 34496870, 2021). "Indeed, in vivo, the blockade of STAT3 phosphorylation results in the inhibition of osteolysis, and tumour growth of metastatic breast cancer." (PMID 34201209, 2021). "Additionally, Ibrutinib-resistant primary CLL cell growth was inhibited by Cerdulatinib, and these anti-tumor effects were proposed to be linked to inhibition of BCR, IL-4/Jak1/Jak3/Stat6 and IL-6/Jak1/Jak2/Stat3 signaling." (PMID 34680353, 2021). "The impaired regulation of NF-κB in tumor cells is also mediated by STAT3 which prompts the retention of NF-κB into the nucleus and hence amplifies its effect during the tumorigenic process and increases the interactions and communication between cancer cells and the microenvironment." (PMID 34744751, 2021). "Blockade of STAT3 also impaired the expression of c-Myc and inhibited tumor growth." (PMID 34829591, 2021). "Therefore, IL-6 can affect the stability of PD-L1 and its binding to PD-1 on immune cells through the IL-6/JAK1/STAT3 pathway, thereby mediating the immune escape of tumor cells." (PMID 34568032, 2021). "Autophagy has been shown to increase STAT3 phosphorylation in multiple tumour models." (PMID 33605033, 2021). "In addition, the JAK2/STAT3 pathway is involved in the SDF-1/CXCR4 interaction promoting mesenchymal stem cell migration in response to the tumor microenvironment." (PMID 34124069, 2021). "Notably, mice also injected with C4HD cells transfected with Stat3 S727A vector showed a reduced growth of tumor, in which the levels of pSTAT3 S727 and of cyclinD1 mRNA were lower as compared with the control." (PMID 34440160, 2021). "Consistently, STAT3 blocking in 4T1 syngeneic mouse markedly suppressed the tumor by triggering CD8+ T cells priming to eliminate tumor cells, which may be manipulated by STAT3-blocking triggered INF-α/β production." (PMID 33957948, 2021). "Furthermore, NT157 represents a new class of anticancer drugs that targets both the IGF-1 receptor (IGF-1R) and the STAT3 oncogenic signaling pathway, exerting an inhibitory effect on tumor cells." (PMID 34445193, 2021). "Because of STAT3’s role in tumor metastasis, we hypothesized that STAT3 might also act as a transcription factor for PD-L1." (PMID 33805840, 2021). "Activated STAT3 in immune cells in the tumor microenvironment in turn induces immune suppression by augmenting production of immunosuppressive cytokines and factors while inhibiting Th1 immunostimulatory mediators, leading to inhibition of antitumor T cell activity." (PMID 33491667, 2021). "Preferential activation of the STAT3 pathway by the permissive cytokine milieu has profound effects on the innate immune system components of the TME, which are largely mediated by tumor-associated macrophages/microglia (TAMs), myeloid-derived suppressor cells (MDSCs), and other cells." (PMID 33498872, 2021). "We next tested to what extent PS-acet.-STAT3 peptide could affect antitumor immune responses in a syngeneic mouse tumor model." (PMID 33491667, 2021). "Thus, this study provides an insight of molecular mechanism of LIN28B/ STAT3 into the tumor-initiation capacity of CCA." (PMID 34837926, 2021). "This underscores the importance of establishing a standardized and robust method of studying CAFs to properly inform how we can exploit STAT3-targeting therapies that target specific CAF subpopulations to tip the balance towards an effective anti-tumor response." (PMID 34858425, 2021). "Therefore, the fact that miR-124 targets STAT3 is an excellent explanation for the molecular mechanism of the anti-tumor effect of miR-124." (PMID 34072894, 2021).
tumor (continued). "Furthermore, MSI1 inhibits miR-671-5p suppression of TNF receptor-associated factor 2 (TRAF2) to induce CSC characteristics and tumor invasion and silence signal transducer and activator of transcription 3 (STAT3) to enhance radioresistance in GBM." (PMID 35052701, 2021). "The authors of the previous study concluded that this effect may be related to the lowest expression level of p-STAT3 and the lowest tumor weight." (PMID 34833950, 2021). "It is critical to inactivate STAT3 to halt tumour progression." (PMID 34707773, 2021). "TNBC tumor cells can autonomously produce IL-6, resulting in the constitutive activation of STAT3." (PMID 34067421, 2021). "In addition, the susceptibility of tumor cells to the NK cytotoxic action was found to be reduced by CAA-derived IL-6 and leptin that activate the JAK/STAT3 signaling axis in tumor cells." (PMID 33917351, 2021). "But it remains to be explored in the future whether STAT3 inhibitors act directly on Treg cells, which consequently alter the TME through tumor-associated antigens." (PMID 33936081, 2021). "Additionally, PGG inhibits STAT3 phosphorylation and induces caspase-mediated apoptosis in prostate cancer cells in vitro and decreases in vivo tumor xenograft growth." (PMID 34502158, 2021). "The activation of STAT3/MMP13 signaling after SIRT1 depletion suggests that SIRT1 may work as a tumor suppressor." (PMID 34769241, 2021). "MiR-506 directly targets STAT3 to exert a tumour suppressor effect." (PMID 34425834, 2021). "Moreover, the expression of STAT3 downstream genes, including c-Myc, Bcl-2 and Bcl-xL in tumor tissue were also downregulated by W2014-S." (PMID 33391507, 2021). "However, in various primary tumors and tumor cell lines, STAT3 and STAT5 remain constitutively active." (PMID 34490234, 2021). "According to the studies present in the literature, our data supported the key role of tumor-SEVs in IL-6 production; in addition, in this study, we correlated the EV-mediated increase in PD-L1 in M0 macrophages to IL-6 release and STAT3 signaling pathway activation." (PMID 34829995, 2021). "It was reported that STAT3 inhibition in combination with radiation improved tumour growth delay, decreased Tregs and enhanced effector T cells and M1 macrophages, which may improve curative effects." (PMID 34059019, 2021). "We next tested whether targeting the gp130/STAT3 signaling axis also represents a potential clinical strategy for other tumor entities." (PMID 33530306, 2021). "Wang and colleagues revealed IL17A promoted tumor progression via STAT3/NF-κB/Notch1 pathway." (PMID 34122408, 2021). "Persistent STAT3 activation promotes tumour progression and metastasis in various cancers." (PMID 34789292, 2021). "Recent evidence suggests that SOCS6 can inactivate the JAK2/STAT3 pathway in tumor cells." (PMID 33937336, 2021). "The structural activation of STAT3 is involved in many cellular processes, including proliferation, survival, inflammation, invasion, metastasis, and angiogenesis, all of which are conducive to tumor initiation and progression." (PMID 34079469, 2021). "A small-molecule inhibitor designed by the binding site could disturb the interaction between CREPT and STAT3, thus interfering the development of STAT3-related tumours." (PMID 33531691, 2021). "Taking STAT3 as an example, experimental research had demonstrated that both baicalin and wogonin could inhibit tumor growth via acting on STAT343,44." (PMID 33558586, 2021). "Furthermore, CPT and imatinib treatment significantly inhibited tumour growth of imatinib resistant K562 cells in vivo through suppression of STAT3 and eIF4E signalling pathways." (PMID 34214017, 2021). "Src/STAT3 signalling in OS may be deactivated by tumour suppressor effect from enamel matrix protein, ameloblastin (AMBN), representing a potential biomarker and therapeutic target for OS." (PMID 33382511, 2021).
tumor (continued). "The inhibition of macrophage CSF1R activity or the enhancement of STAT3 activation in the TME can promote the repolarization of M2 macrophages to a phenotype similar to M1 to overcome the immunosuppressive state that promotes tumor growth and metastasis." (PMID 34683963, 2021). "Furthermore, STAT3 activation in tumors can be transmitted to immune cells in the tumor microenvironment through secreting mediators such as IL-6 among many other cytokines and growth factors." (PMID 33491667, 2021). "Since STAT3 is involved in the polarization of neutrophils to a “N2” phenotype, small drugs targeting this pathway are expected to have a beneficial anti-tumor effect." (PMID 34572138, 2021). "Moreover, STAT3 activity reduces the migration of various immune cells to the tumour microenvironment involving NK cells, T cells, neutrophils, and macrophages, further contributes to an immunosuppressive tumour microenvironment." (PMID 33922087, 2021). "STAT3 dysregulation is thought to be involved with tumour progression, angiogenesis and metastasis." (PMID 33382511, 2021). "Under hypoxic conditions, STAT3 physically interacts with programmed cell death protein-L1 (PD-L1) and facilitates its nuclear translocation, enhancing the macrophage-derived TNFα-induced tumor necrosis in vivo, and correlates with chemotherapeutic drugs." (PMID 35096565, 2021). "Furthermore, phosphorylation status of EGFR at Y1068 and Y1173 along with the downstream mediator STAT3 (Y705) was shown to decrease in tumor tissue in Anthos treated mice." (PMID 34926717, 2021). "Cell culture experiments revealed that MC38 tumor-derived factors directly promote myotube wasting (−18%) and STAT3 phosphorylation (+5-fold), while the pharmacologic blockade of STAT3 signaling was sufficient to preserve myotube atrophy in the presence of MC38 cells (+21%)." (PMID 33540821, 2021). "Thus, STAT3 is part of a particularly interconnected circuit, with multiple roles in tumor progression, evasion of the immune response, anti-apoptotic activity, angiogenesis, etc.." (PMID 34067120, 2021). "SOCS3 expression is reduced during progression from active UC to IBD-CRC and the altered methylation of SOCS3 may be involved in tumor progression increasing STAT3 signaling." (PMID 34744751, 2021). "Studies had shown that KIF20A might promote the proliferation, invasion and migration of tumor cells by activating the JAK2/STAT3 pathway." (PMID 33836688, 2021). "IL-6 is the major cytokine that stimulates proliferation of tumor cells, and it inhibits apoptosis via activation of the STAT3 signaling pathway 18 TNF-α could activate NF-κB and AKT signaling cascades and stimulate tumor progression." (PMID 33391471, 2021). "Genetic abnormalities may affect the cytokine/JAK/STAT3 pathway to induce the activation of STAT3 that may contribute to an immunosuppressive tumor microenvironment (TME)." (PMID 35582375, 2021). "In addition, IL-6 is a potent activator of signal transducers and activators of the transcription (STAT) factors STAT1 and STAT3, which play an important role in the progression of neoplasia." (PMID 33922946, 2021). "Moreover, vesicular TGF-β induces proinflammatory IL-6 production by MSCs, allowing the tumor EV-educated mesenchymal stem cells to promote osteosarcoma progression together with intratumor STAT3 activation and lung metastasis formation." (PMID 34830463, 2021). "In addition, the protein expression levels of p-JAK2 (Y1007/1008) and p-STAT3 (Tyr705) in the tumor tissues of nude mice in the LNT group were significantly reduced by western blot." (PMID 34900727, 2021). "Furthermore, treating CD19+ B cells and peritoneal macrophages from tumor naïve mice with Olaparib also activated STAT3." (PMID 34956861, 2021).
tumor (continued). "Exosomal miR-503 derived from tumour cells promotes M1-M2 conversion of microglia through manipulating STAT3 and NF-κB signalling pathways, followed by enhancing their PD-L1 expression to suppress local immunity and thereby promote brain metastases of breast cancer." (PMID 35006432, 2021). "STAT3 plays an essential role in tumor progression and tumor immunity." (PMID 34806028, 2021). "Since SHP099, differently from MEK inhibitors, failed to induce STAT3 activation in B16F10 cells, these results raise the possibility that STAT3 activation may be a critical contributor to growth inhibition in B16F10 tumor cells." (PMID 34102002, 2021). "STAT3 is expressed strongly in all cases of the three tumour types." (PMID 34680385, 2021). "Likewise, lung cancer-derived ExVs induced DCs to produce IL-6 which promoted tumor invasion by increasing STAT3-dependent MMP 9 transcription activity in tumor cells." (PMID 33435564, 2021). "STAT3 is an important transcription factor in tumor progression." (PMID 33660414, 2021). "Therefore, IFN-γ supports the promotion of tumorigenesis by immune evasion, in OSCC-GB patients, through activation of PDL1 transcription in tumor cells via the IL6/JAK/STAT3 signaling pathway." (PMID 33980865, 2021). "Notably, studies have demonstrated the general increase in the levels of STAT3 in HCC tumor tissue samples and activated nuclear STAT3 was observed in approximately 60% of HCC samples, which was correlated with malignant progression and negative prognosis." (PMID 35053027, 2021). "Furthermore, we investigated the effect of nifuroxazide on IL-6/jak2/STAT3 signaling and the possible impact on tumor angiogenesis." (PMID 34833950, 2021). "In addition, IL6 upregulates Mcl-1 (an apoptosis inhibitor) enhancing tumour cells survival by increasing expression of STAT3." (PMID 33579265, 2021). "In addition to the important role of STAT3 in the pathogenesis of vascular disease, ischemia and other tissue injuries, STAT3 is aberrantly overexpressed in many human tumor types and correlates with poor cancer prognoses." (PMID 34542605, 2021). "Moreover, in PC models, STAT3 activity in tumor-infiltrating MDSCs correlated with increased PD-L1 levels and elevated plasma levels of IL6-type cytokines (such as LIF), suggesting a potential cross-talk mechanism promoting tumor immune evasion." (PMID 34830209, 2021). "TGFβ1, as one of the most important factors of modulating the function of DCs in tumor microenvironment, has been proved that could induce DCs tolerance directly, or increase the expression of PD-L1 on DCs in a STAT3 dependent manner." (PMID 34249724, 2021). "STAT3 inhibition in tumour cells resulted in the production of pro‐inflammatory cytokines and chemokines, leading to activation of the anti‐tumour innate immune response, DCs activation and tumour‐specific T‐cell response." (PMID 33382511, 2021). "IL-6 directly stimulates the expression of STAT3 downstream targets in tumor cells." (PMID 35155571, 2021). "STAT3 acts as a potential tumor-promoting transcription factor that gets aberrantly activated in several types of human cancers and plays a crucial role in tumor progression and metastasis." (PMID 35053027, 2021). "Furthermore, elevated levels of IL-6 stimulated the hyperactivation of STAT3 signalling, which is often correlated with tumour progression." (PMID 34369236, 2021). "STAT3 can also orchestrate NF-κB-mediated transcription and promote pro-tumor chronic inflammation." (PMID 33800829, 2021). "This may be due to the intrinsic activation of STAT3 in tumor cells through genetic or epigenetic mechanisms, which can promote the differentiation of suppressive cells in the tumor microenvironment." (PMID 33692217, 2021). "Therefore, targeting STAT3 can not only directly inhibit tumor growth but also enhance antitumor immunity." (PMID 34326876, 2021). "It has been shown that miR-125b-5p displays a tumor-suppressive role via targeting STAT3." (PMID 33921710, 2021).